SEMA3D (semaphorin 3D)
Diseases named in the same sentence as SEMA3D in open-access papers (continued):
Sharing a sentence is not in itself a finding about the gene and the disease.
tumor (23 papers, 2008 to 2025). "In PDAC, tumor- and nerve-derived Sema3D reprogram macrophages indirectly via KRAS mutation-dependent adenosine diphosphate-ribosylation factor 6 (ARF6) signaling in tumor cells." (PMID 41163091, 2025). "Our previous integrative genomic studies in ccRCC detected missense variants of Sema3D (amino acid change of D186 N) in both primary tumor and tumor thrombus from a patient with metastatic ccRCC." (PMID 35813868, 2022). "Low expression of Sema3D was associated with advanced tumor stage, advanced histological grade, and poor prognosis in ccRCC." (PMID 35813868, 2022). "The immune infiltration correlation analysis in this study suggested several immune cells (neutrophils, eosinophils, and T helper cells) were highly associated with Sema3D in the tumor microenvironment." (PMID 35813868, 2022). "By analyzing the data from TCGA database and validating the results in the TMA samples, we found lower Sema3D expression in ccRCC tumor tissues than para-tumor tissues, and low Sema3D level was associated with poor prognosis in ccRCC patients." (PMID 35813868, 2022). "The presence of tumor also induced upregulation of Sema3d, which encodes the ligand for plexin D1 and is involved in angiogenesis, in adjacent normal ECs." (PMID 32440964, 2020). "Reducing SEMA3D or its receptor plexin D1 expression inhibits the invasion of tumor cells towards the nerves and decreases the nerve density in tumor tissues." (PMID 37610689, 2024). "The reason of not evaluating T stage and tumor size as prognostic indicators was likely to be the correlation between Sema3D expression and T stage, which covered the intrinsic roles of T stage and tumor size in the survival outcomes." (PMID 35813868, 2022). "In this study, by validating the correlation between tumor Sema3D expression level and the prognosis of ccRCC patients, we identified the cancer suppressive role of Sema3D." (PMID 35813868, 2022). "The protein expression level of Sema3d in tumor tissues and cell lines was detected by Western blot, consistent with the GEO and TCGA datasets." (PMID 35957887, 2022). "It is supported in another study that tumor cells expressing Sema3D can travel toward PlxnD1-expressing neurons, according to their Diagnosis Related Groups (DRG) in vitro data." (PMID 36713527, 2022). "Compared to 86 tumor specimens, we confirmed the Sema3D expression level was higher in paired para-tumor tissues (p < 0.001)." (PMID 35813868, 2022). "Semaphorin 3C (Sema3C) and semaphorin 3D (Sema3D) play an important role in tumor development by regulating cell proliferation, migration, invasion, and angiogenesis processes." (PMID 35350431, 2022). "Taken together, reduced Sema3D expression level was an independent predictor of poor prognosis for ccRCC patients, suggesting Sema3D in tumor tissue can be a potential prognostic biomarker for localized ccRCC patients." (PMID 35813868, 2022). "Several subtypes of tumor-infiltrating immune cells were found correlated with the Sema3D expression level, including neutrophils (r = 0.301, p < 0.001), T helper cells (r = 0.215, p < 0.001), and eosinophils (r = 0.193, p < 0.001)." (PMID 35813868, 2022). "In summary, our study identified the transmembrane transporter Sema3D as a tumor suppressor in ccRCC, and the Sema3D protein expression level was an efficient prognostic biomarker for localized ccRCC patients." (PMID 35813868, 2022). "To investigate the intrinsic role of Sema3D in the immune microenvironment in ccRCC, we then analyzed the correlation between Sema3D expression and tumor-infiltrating immune cells by identifying matching cell markers." (PMID 35813868, 2022). "It was reported that Sema3D had strong anti-angiogenic effects in a glioma tumor model of mice, which suggested potential tumor suppressive function by inhibition of tumor angiogenesis of Sema3D." (PMID 35813868, 2022).
tumor (continued). "elucidated one mechanism of PDA metastasis formation: Sema3D can bind to PlxnD1 on the surface of PDA tumor cells in the extracellular space by the regulation of its autocrine function control of AnxA2." (PMID 36713527, 2022). "Our study suggested that the interaction with coagulation system, KRAS signaling, and tumor neutrophil infiltration were the potential mechanisms of Sema3D serving as a tumor suppressor in ccRCC." (PMID 35813868, 2022). "In 86 ccRCC patients, Sema3D mRNA and protein expression were downregulated in tumor tissues than the para-tumor tissues, and Sema3D was dominantly expressed in the extracellular space." (PMID 35813868, 2022). "Transmembrane transporter Sema3D is an efficient prognostic biomarker for localized ccRCC patients, by playing the role of tumor suppressor in ccRCC." (PMID 35813868, 2022). "Among the tumor specimens with IDH mutation, mRNA levels of SEMA3B, SEMA3C, SEMA3D, SEMA3G, NRP2, PLXNA2, and CDH1 were significantly higher (p < 0.05), while SEMA3F, NRP1, ITGB3, ITGA5, and VEGFA genes were under-expressed (p < 0.05)." (PMID 33036421, 2020). "SEMA3D is found to inhibit tumour growth in colorectal and breast cancers, but it correlates with metastatic disease and worse survival in patients with pancreatic cancer." (PMID 32241267, 2020). "In agreement with this study, we also noticed similar tendencies of SEMA3B, SEMA3G, SEMA3D and VEGFA mRNA level associations with patient survival and tumor malignancy grade." (PMID 33036421, 2020). "Patient age, tumor grade, status of IDH mutation and expression of seven genes (SEMA3A, SEMA3D, SEMA3F, SEMA3G, ITGB3, ITGA5, and VEGFA) significantly correlated with patient OS (p < 0.05)." (PMID 33036421, 2020). "Like other class-3 semaphorins, sema3D seems to inhibit tumor progression and inhibit angiogenesis, although there is also some evidence suggesting that it too can have a dual role and promote tumor progression under certain circumstances." (PMID 30696103, 2019). "It controls the interaction between Sema3D and its receptor plexin D1 (PlxnD1) on the tumor cell surface, thereby promoting tumor invasion and metastasis." (PMID 29290958, 2017). "Since sema3D and sema3E seemed to be the most potent inhibitors of tumor formation from U87MG cells, we extended these in-vivo studies to determine if the expression of these semaphorins would also inhibit tumor development from another GBM derived cell line." (PMID 22936999, 2012). "It is thus likely that a major part of the anti-tumorigenic effects of sema3D and sema3E is mediated through inhibition of tumor angiogenesis." (PMID 22936999, 2012). "Sema3E and sema3D seemed to be the most effective inhibitors and abrogated almost completely tumor development in spite of their marginal effect on cell proliferation in-vitro." (PMID 22936999, 2012). "The np2agonist sema3F also inhibited tumor formation effectively although somewhat less effectively than sema3E and sema3D." (PMID 22936999, 2012). "As in the previous experiment, we found that expression of sema3D or sema3E almost completely inhibited tumor development from cells implanted in the brain cortex of mice (data not shown)." (PMID 22936999, 2012). "Here too, expression of sema3E and sema3D in the tumor cells significantly prolonged the survival of the mice." (PMID 22936999, 2012). "Our results indicate that sema3D also functions as an inhibitor of angiogenesis and suggest that the anti-tumorigenic effects are due primarily to inhibition of tumor angiogenesis." (PMID 22936999, 2012). "Sema3A, sema3D, sema3E and sema3G overexpression in breast cancer cells significantly inhibits the development of tumor in xenograft models and decreases the number of intra-tumor blood vessels, suggesting an anti-angiogenic role of these molecules." (PMID 24212788, 2011).
tumor (continued). "In conclusion, we have found for the first time that the semaphorins sema3A, sema3D, sema3E and sema3G possess anti-tumorigenic and anti-angiogenic properties similar to those displayed by the previously identified tumor suppressor sema3F." (PMID 18818766, 2008). "We have presented here for the first time evidence indicating that sema3D, sema3G sema3E and sema3A can significantly reduce the concentration of microvessels in tumors that develop from tumor cells that express these semaphorins." (PMID 18818766, 2008). "In contrast, the np2 agonist sema3G was unable to inhibit tumor development from these cells, although it was highly expressed as compared to sema3D." (PMID 18818766, 2008). "Finally, we proved that Sema3d exerted its tumor-restraining effect by interacting with FLNA to inactivate the Pi3k/Akt signaling pathway and remodel the cytoskeleton." (PMID 35957887, 2022). "The Sema3D mRNA expression profile in ccRCC showed a lower expression level of Sema3D in tumor tissues compared with normal tissues (p < 0.001), suggesting that low expression of Sema3D may be involved in the development of ccRCC." (PMID 35813868, 2022). "Correlation analysis between Sema3D and tumor-infiltrating lymphocytes was calculated by ssGSEA." (PMID 35813868, 2022). "Bioinformatics analysis showed the correlation between low Sema3D level and advanced tumor stage." (PMID 35813868, 2022). "Intriguingly, higher mRNA expression of SEMA3D mRNA has been observed in normal colorectal mucosa, as compared to the CRC tissues, suggesting that SEMA3D may function as a tumour suppressor gene in CRC progression." (PMID 34573430, 2021). "Although promising, these in vivo findings leave open the question of whether local or systemic administration of the soluble forms of Sema3A, Sema3D, Sema3E, or Sema3F may recapitulate the tumor-suppressing effect of ectopically expressed molecules." (PMID 31052281, 2019). "Little is known about the roles of sema3D and sema3G in tumor progression." (PMID 30696103, 2019). "The current study indicated that SEMA3D might function as a tumor suppressor during the formation and development of CRC." (PMID 28320475, 2017). "We also determined whether sema3D, sema3F and sema3G, which inhibit tumor formation from MDA-MB-435 cells, also inhibit the anchorage free growth of these cells." (PMID 18818766, 2008). "However, the expression of sema3A and sema3D, semaphorins that strongly inhibited tumor formation from these cells, also inhibited significantly the formation of large colonies in soft agar." (PMID 18818766, 2008). "Lower mRNA expression of SEMA3B, SEMA3D, SEMA3G, and PLXNA2 or higher mRNA expression of SEMA3F, NRP1, ITGB3, ITGA5, and VEGFA genes were detected in the older patient group and associated with the higher tumor grade, wild-type status of IDH, and lower rate of survival time (p < 0.05)." (PMID 33036421, 2020). "SEMA3D might function as a tumor suppressor during the formation and development of CRC." (PMID 28320475, 2017). "In relation to the malignancy grade of the tumor, mRNA levels of SEMA3B, SEMA3C, SEMA3D, SEMA3G, PLXNA2, and CDH1 decreased while mRNA levels of SEMA3F, NRP1, ITGB3, ITGA5, and VEGFA increased with the increase of the tumor malignancy (p < 0.05)." (PMID 33036421, 2020). "All other SEMA3 family members show inconsistent up- or down-regulation in different cancer tumours, where SEMA3B, SEMA3D, SEMA3E, and SEMA3G are primarily down-regulated, and SEMA3A and SEMA3C are mainly up-regulated in the tested cancer types." (PMID 32241267, 2020). "Whereas SEMA3A, SEMA3C, and SEMA3F were mainly up-regulated in the tested tumours, the rest of the members SEMA3B, SEMA3D, SEMA3E and SEMA3G were primarily down-regulated with a few exceptions." (PMID 32241267, 2020).
tumor (continued). "We observed that levels of SEMA3 expression showed great heterogeneity in different cell lines as in patient tumours, with SEMA3C having the highest expression and SEMA3D having the lowest expression across all cancer cell lines." (PMID 32241267, 2020). "Sema3D also displayed very potent inhibitory effects and also inhibited relatively poorly the proliferation of the tumor cells, but its anti-angiogenic potential had not been determined yet." (PMID 22936999, 2012). "It is not known whether Sema3D or 6D can function similarly in the retina but all three of these have functional role in either inhibiting or promoting tumor angiogenesis." (PMID 35933488, 2022). "However, there are no additional studies that relate to the possible role of sema3D in tumor progression." (PMID 30696103, 2019). "Sema3D, an agonist for both np1 and np2, inhibited tumor formation completely in one experiment (data not shown) and in another experiment inhibited strongly though not completely tumor development even though it was not as highly expressed as the other semaphorins." (PMID 18818766, 2008). "In the case of tumors that develop from np2 expressing MDA-MB-435 cells, we found that the expression of sema3A and sema3D reduced the concentration of blood vessels in resulting tumors by 65% even though tumor development from these cells was not inhibited at all by sema3A." (PMID 18818766, 2008). "Moreover, overexpression of Sema3d in HCCLM3 cells was significantly inhibited and knockdown of Sema3d in PLC/PRF/5 cells promoted proliferation, migration, invasion, and epithelial–mesenchymal transition (EMT) of HCC cells in vitro and tumor growth, EMT, and metastasis in vivo." (PMID 35957887, 2022). "In contrast, expression of sema3A did not inhibit tumor development, while sema3D which binds to both neuropilins, significantly inhibited tumor development from the MDA-MB-435 cells though less potently than sema3G which may be due to the lower expression levels obtained with sema3D in these cells." (PMID 18818766, 2008). "Interestingly, even though Sema3D and sema3E inhibited either proliferation or anchorage free growth of the U87MG cells in-vitro much less effectively than sema3A, they still inhibited subcutaneous tumor development as effectively as sema3A if not more effectively." (PMID 22936999, 2012).
cancer (12 papers, 2008 to 2024). A tumor composed of atypical neoplastic, often pleomorphic cells that invade other tissues. "We investigated the level of Sema3D expression in pan-cancer and matching normal tissues in GEPIA2 database." (PMID 35813868, 2022). "Semaphorin 3d (Sema3d) has been shown to play a critical role in vascular development during early embryogenesis and several forms of cancer progression via regulating cell migration." (PMID 35957887, 2022). "SEMA3D, a membrane-bound protein, is involved in cell-cell communication and plays an important role in many pathophysiological processes, such as cancer development, and its overexpression has been related to increased cell invasiveness." (PMID 33324695, 2020). "Moreover, Sema3D-depeleted cancer showed decreased invasive and metastatic potential in culture and in mouse models." (PMID 33537086, 2021). "Very interestingly, we found that SEMA3B, SEMA3D, SEMA3E, and SEMA3G genes were negatively associated with RNAss and DNAss (P < .0001), where the strongest association was observed for SEMA3G with RNAss (r = − 0.49) across cancer types." (PMID 32241267, 2020). "We found that SEMA3B, SEMA3D, SEMA3E, and SEMA3G were all negatively associated with cancer-stem like features, but SEMA3A, SEMA3C, and SEMA3F were positively correlated with DNAss, which indicates that SEMA3s may associate with cancer cell sensitivity or resistance to chemotherapy treatment." (PMID 32241267, 2020). "Importantly, several recent studies have investigated the role of SEMA3D in cancer." (PMID 28320475, 2017). "Semaphorins (such as SEMA3D and SEMA4D) are characterized by aberrant expression in several cancer types and contribute to cancer initiation." (PMID 39766161, 2024). "SEMA3A, SEMA3D, and SEMA3E showed relatively lower level of expression averaged across all cancer types compared to the rest of the SEMA3 family members.i.e., SEMA3B, SEMA3C, SEMA3F and SEMA3G, where SEMA3F had the highest expression." (PMID 32241267, 2020). "One cluster includes SEMA3D, SEMA3E, SEMA3G and PLXNA4, which all showed primarily down-regulation in the tested cancer tumors." (PMID 32640719, 2020). "Thus, SEMA3D may be a potential serological marker for cancer." (PMID 28320475, 2017). "However, SEMA3D has no reports in the context of cancer, except for an indirect suggestion of anti-tumorigenic activity." (PMID 29074988, 2017).
SEMA3D also shares sentences with these, for which no sentence is quoted: Aganglionic megacolon (1 paper); brain cancer (1); bursitis (1); cervical cancer (1); colorectal cancer (1); Crohn disease (1); disc degeneration (1); endothelial dysfunction (1); genetic disorder (1); intellectual disability syndrome (1); Knee Osteoarthritis (1); liver cancer (1); melanoma (1); Meniere disease (1); Mowat-Wilson syndrome (1); neurodegenerative disease (1); rheumatoid arthritis (1); thymoma (1); uterine cancer (1).